CRP (C-reactive protein)
Diseases named in the same sentence as CRP in open-access papers (continued):
Sharing a sentence is not in itself a finding about the gene and the disease.
COVID-19 (continued). "Future studies with appropriate controls, serial inflammatory and coagulation biomarkers (e.g., IL-6, CRP, D-dimer), and vessel-wall imaging could better delineate whether a subset of SAH during COVID-19 reflects causal biology versus coincidence." (PMID 41458771, 2025). "As expected, CRP showed a strong and highly significant association with IL6, confirming prior studies that have consistently demonstrated the IL6–CRP axis as a central pathway in COVID-19-related inflammation." (PMID 41373577, 2025). "In COVID-19, children > 6 months more frequently had higher CRP levels." (PMID 41305426, 2025). "Also, Age at admission, Pf ratio (PaO2/FiO2 ratio), troponin T (TropT), ferritin, ventilation, C-reactive protein (CRP), and symptoms of acute respiratory distress syndrome (ARDS) were associated with the severity and fatality of COVID-19 cases." (PMID 39820088, 2025). "Importantly, C-reactive protein (CRP), a key inflammatory marker, was markedly lower in the COVID-19 group (26.0 vs. 47.8 mg/dL, p < 0.001), suggesting a milder inflammatory response at presentation." (PMID 41465760, 2025). "Multivariable analyses adjusted for known risk factors (age, gender, blood counts, lactate dehydrogenase, c-reactive protein, underlying disease) showed that CC16 levels were independently associated to COVID-19 severity (interquartile-range, odds ratio 1.53, p=0.0102)." (PMID 40236699, 2025). "C-reactive protein (CRP) levels tend to rise in COVID-19 patients due to inflammatory cytokines." (PMID 40901150, 2025). "However, after distinguishing between influenza A and B, we observed that children with influenza A in 2024 and 2015–2016 had higher rates of CRP > 1 mg/dL or CRP > 3 mg/dL compared to those with influenza B in 2015–2016 or COVID-19." (PMID 40142409, 2025). "Levels of CRP > 100 mg/L at initial presentation increased the risk of venous thromboemboli in COVID-19 patients, whereas severity of the thrombotic events was not specified." (PMID 40909455, 2025). "In COVID-19, children older than 6 months more frequently had higher CRP levels." (PMID 41305426, 2025). "In conclusion, elevated RDW and CRP levels at admission may be reliable predictors of unfavorable outcomes, emphasizing the utility of these indicators in clinical assessments of COVID-19 patients." (PMID 40362375, 2025). "Additionally, s-CRP concentration was higher in patients with critical COVID-19 on VV-ECMO compared to severe COVID-19 patients (P < 0.050)." (PMID 39862311, 2025). "Comparison of the blood test results of the two groups revealed that the median WBC was 5,240/μl and 10,770/μl in the COVID-19 and non-COVID-19 group, respectively (p<0.05) while the median CRP value was 0.05 mg/dl and 0.29 mg/dl (p<0.05) for the respective group." (PMID 40821183, 2025). "Inflammatory markers such as CRP and D-dimer, along with immune response indicators (anti-RBD IgG and IgM), exhibited particularly strong associations with severe ARDS cases, aligning with established clinical patterns of COVID-19." (PMID 40860652, 2025). "Accordingly, CRP and Ferritin levels are elevated in COVID-19 patients." (PMID 41007829, 2025). "Moreover, patients with MIS present more often neutrophilia and thrombocytopenia than lymphocytopenia and have higher levels of pro-inflammatory biomarkers (e.g. CRP and IL-6) within 48 h from admission compared to patients with COVID-19." (PMID 39775145, 2025). "In contrast, previous studies have reported a positive association with CRP but not with procalcitonin in COVID-19 patients." (PMID 40143286, 2025). "Interestingly, parameters demonstrating an increase in case of moderate/severe COVID-19 (e.g. CRP, APTT, IL-18) negatively correlated with the days elapsed since the positive SARS-CoV-2 test result." (PMID 40303405, 2025). "The elevation of CRP levels reflects an exaggerated inflammatory response in COVID-19 patients." (PMID 40861215, 2025).
COVID-19 (continued). "CRP (Mann–Whitney U = 24655, p = 0.008), IL-6 (Mann–Whitney U = 12010, p = 0.0003), and ferritin (Mann–Whitney U = 7585, p < 0.0001) were largely increased in severe COVID-19 male patients." (PMID 40868247, 2025). "A broad range of clinical biomarkers, such as total leukocyte levels, lymphocyte and neutrophil measurements, along with inflammatory markers like CRP, PCT, and IL-6, have been thoroughly explored in prior research and linked to both the progression and fatal outcomes of COVID-19." (PMID 41309368, 2025). "This may reflect greater anemia prevalence in those with other infections or, a milder inflammatory burden in COVID-19, supported by lower CRP levels." (PMID 41465760, 2025). "Similarly, inflammatory cytokines including IL-6, tumor necrosis factor-alpha (TNF-α), and CRP were elevated in patients with COVID-19 at baseline compared with levels in healthy controls in both the RoW and US studies." (PMID 40461100, 2025). "Severe COVID-19 is frequently characterized by a hyperinflammatory state, often termed a “cytokine storm,” which entails elevated levels of interleukin-6 (IL-6), C-reactive protein (CRP), and other pro-inflammatory cytokines." (PMID 39857695, 2025). "Also, multiple logistic regression showed that age, smoking, COVID-19 severity, taking anti-CD20 monotherapy and CRP and NLR values on day 1 were significantly associated with death." (PMID 40559558, 2025). "In addition, in acute COVID-19 populations, S100B concentrations correlated significantly with organ injury indicators and inflammation markers, including C-reactive protein (CRP)." (PMID 40048451, 2025). "Furthermore, IL-6, CRP, D-dimer, and ferritin were significantly higher in severe forms of COVID-19." (PMID 40868247, 2025). "The results revealed that polymorphisms in the IL6, IL6R, IL1α, IL1R, IFNγ, TNFα, CRP, VDR, VDBP, and ACE2 genes are the most significant genetic factors influencing COVID-19 prognosis, particularly in terms of the risks of COVID-19 pneumonia, mortality, rehospitalization, and associated mortality." (PMID 40869297, 2025). "CRP is one of the oldest clinical biomarkers used widely in routine clinical practice worldwide, and its use increased during the COVID-19 pandemic as a marker of disease severity and prognosis." (PMID 39877415, 2025). "In addition to elevated levels of high-sensitivity C-reactive protein (hs-CRP), COVID-19 patients with myocardial injury also presented with low lymphocyte count, and high levels of IL-6, IL-8, N-terminal pro-B-type natriuretic peptide (NT-proBNP) and TNF-α." (PMID 40438117, 2025). "Apart from D-dimers and Blood pH, other factors include age at admission, PaO2/FiO2 ratio (Pf_Ratio), TropT, Ferritin, ventilation, CRP, and Symptom of Acute respiratory distress syndrome (ARDS) also have a strong association with the severity and fatality of COVID-19 cases." (PMID 39820088, 2025). "Patients with COVID-19 exhibit elevated blood levels of inflammatory markers, including C-reactive protein, lactate dehydrogenase (LDH), creatine phosphokinase (CPK), ferritin, D-dimer, and troponin-I, with a concomitant increase in the neutrophil-to-lymphocyte ratio and other inflammatory markers." (PMID 40142738, 2025). "Overall, the MR studies included in this review do not support a causal association between VD and COVID-19 outcomes or related inflammation markers, except in the case of VD deficiency and CRP." (PMID 39449666, 2025). "We showed that creatinine and urea were in strong positive correlation with clinical outcome, while it has been reported that the most important predictors of COVID-19 mortality were age, glomerular filtration, urea, CRP, ferritin, ALT, creatinine, and leukocytes." (PMID 40868247, 2025). "Conversely, in patients with fever who tested negative for COVID-19, the presence of slimy or greasy tongue fur was associated with the level of C-reactive protein." (PMID 40854033, 2025).
COVID-19 (continued). "In previous studies, various clinical information such as baseline age (P = 0.014), CRP (P = 0.035), AST (P = 0.027), and D-Bil (P = 0.001) levels may be significantly associated with disease regression in patients with COVID-19." (PMID 41585243, 2025). "As we have already mentioned, biomarkers such as CRP, D-dimer, and IL-6 are clear predictive markers and have been used in clinical care for some time, since they are significantly expressed in patients hospitalized with COVID-19." (PMID 39859366, 2025). "During the course of COVID-19, cytokine storms lead to enhanced CRP production in adult patients." (PMID 39967737, 2025). "However, C-reactive protein (CRP), D-dimer, and ferritin were elevated, indicating an inflammatory state related to COVID-19." (PMID 40106947, 2025). "The high mortality rate in deceased people infected with COVID-19 with GG genotype could be due to their higher serum CRP levels." (PMID 38184750, 2024). "The study indicates that IV dexamethasone may offer superior benefits in managing certain biochemical parameters like CRP, HB, and oxygen saturation in COVID-19-related ARDS compared to inhaled budesonide." (PMID 39065649, 2024). "Elevated levels of CRP, an acute-phase reactant produced in response to inflammation, have been proposed as prognostic markers for severe COVID-19 and may reflect the extent of tissue injury and systemic inflammatory burden." (PMID 39087175, 2024). "In a cohort study of 100 patients who recovered from COVID-19, statistically significant discrimination between controls and post-COVID cases was reported using C-reactive protein (CRP), a blood biomarker that positively correlates with the incidence of thrombosis." (PMID 39337860, 2024). "Serum CRP has been identified as an important marker in patients with severe COVID-19." (PMID 38450049, 2024). "CRP, as a marker of inflammation, tends to be elevated in patients with COVID-19." (PMID 39518325, 2024). "The exact effect of CRP on COVID-19 is unknown, although it has been reported that its level can be utilized for the early detection of pneumonia and the assessment of severe lung infectious disorders." (PMID 39407172, 2024). "Another difference may relate to markers of inflammation—patients with COVID-19 often have very high levels of C-reactive protein (CRP), ferritin, and D-dimer, as well as increased neutrophils and decreased lymphocytes." (PMID 39063142, 2024). "Overall, establishing the complex relationship between high altitude, IL-6, hepcidin, ferritin, C-reactive protein, and zinc in the context of COVID-19 could provide insight into the pathogenesis of the disease." (PMID 39062181, 2024). "The elevated levels of CRP, procalcitonin, and ferritin in diabetic patients suggest that pre-existing inflammatory states may exacerbate the inflammatory response to COVID-19, leading to worse outcomes." (PMID 39338165, 2024). "In addition, triglycerides, were also found to be upregulated in COVID-19 patients and it positively correlates with pro-inflammatory markers such as interleukin-6 (IL-6) and C-reactive protein (CRP)." (PMID 38799469, 2024). "Studies show that a positive correlation exists between IL-6 and CRP levels in COVID-19 patients." (PMID 38655258, 2024). "There were elevated levels of LDH, D-dimer, serum ferritin, and CRP across the three age groups of COVID-19 patients, indicating an exaggerated immunological response and cytokine storm syndrome, which may contribute to disease pathogenicity and mortality." (PMID 39195007, 2024). "Our study included COVID-19 patients hospitalized with mild respiratory failure, all of whom received steroid treatment, and we assessed changes in serum CRP, procalcitonin, neutrophil, and lymphocyte values on the third day of treatment as potential predictors of worsening respiratory failure." (PMID 39685844, 2024).
COVID-19 (continued). "CRP has been recognized as the outcome predictor and discriminator of COVID-19 disease severity, and therefore its population-specific measurement encompasses the diagnostic/prognostic value for the disease, COVID-19, and may have a remarkable clinical impact." (PMID 38610151, 2024). "Similarly, in our study, a positive correlation was observed between elevated neopterin levels and increased CRP levels in patients with severe COVID-19." (PMID 39058886, 2024). "Mounting evidence supports a positive correlation between CRP levels and the severity of COVID-19." (PMID 39661669, 2024). "Therefore, the addition of dornase alfa to dexamethasone resulted in a significant and sustained reduction in CRP in a greater number of COVID-19-infected participants compared to treatment with dexamethasone alone." (PMID 39009040, 2024). "Furthermore, sensitivity analysis revealed the high importance of PT, ESR, ALT, BUN, PTT and CRP in the hospital stay prediction of male COVID-19 patients." (PMID 38263446, 2024). "When directly looking at the specific cytokines found to be able to predict the NfL levels (CRP, IL-4, IL-8, IL-9, Eotaxin, and MIP-1ß), the literature highlight that all the selected factors are highly up-regulated during COVID-19 and associated with clinical outcomes." (PMID 39125829, 2024). "Studies have concluded that in critically ill COVID-19 patients, CRP and PCT have shown rebound increases upon cessation of immunomodulator treatment, and as such, clinicians should assess basic clinical infection signs and cultures for diagnosis of secondary bacterial infections." (PMID 39290622, 2024). "The overproduction of inflammatory cytokines in patients with severe COVID-19 may be responsible for the high levels of CRP." (PMID 39407172, 2024). "This suggested that while the bodily response to SARS-CoV-2 infection was robust, HBV super-infection might have little impact on CRP levels in COVID-19 patients." (PMID 39699512, 2024). "In addition, some of other biomarkers have been reported to indicate mortality and prognosis in COVID-19, including lymphocytes, CRP and fibrinogen." (PMID 38390620, 2024). "Combinations of high CRP levels and low oxygen saturation levels indicate severe COVID-19." (PMID 38623185, 2024). "However, tocilizumab, an interleukin-6 receptor inhibitor, which is a standard adjunctive therapy in severe COVID-19 with high levels of C-reactive protein (CRP), is relatively contraindicated in pregnancy." (PMID 39223684, 2024). "Systemic inflammation markers, CRP/albumin ratio, neutrophil/lymphocyte ratio, and platelet/lymphocyte ratio were significantly higher, while lymphocyte/monocyte ratio was also significantly lower in patients with severe COVID-19 than in healthy volunteers." (PMID 39058886, 2024). "Statistical data showed that the severity of COVID-19 could be predicted at a cutoff value of CRP > 30 mg/L, with a sensitivity of 74.3% and a specificity of 42.9%." (PMID 39407172, 2024). "Among COVID-19, serum concentrations of D-dimer and hs-CRP were higher in patients with ARDS." (PMID 39456513, 2024). "Various studies have proposed CRP as a marker of severity and mortality in patients with COVID-19." (PMID 39685758, 2024). "Conversely, an elevated level of CRP during COVID-19 was a predictor of recovery." (PMID 38510249, 2024). "Older age, male gender, risky occupations, fever, headache, muscle ache, dyspnea, diarrhea, diabetes mellitus, heart disease, bronchial asthma, lower platelets, low absolute lymphocytic count, higher NLR, PLR, CRP, transferrin, LDH, and D dimer were associated with more-severe COVID-19." (PMID 39452786, 2024). "We speculated that prompt corticosteroid administration to COVID-19 patients could mitigate vigorous host respiratory and systemic inflammatory responses, as evidenced by reduced CRP levels." (PMID 38304653, 2024).
COVID-19 (continued). "Additionally, the inflammatory marker hs-CRP was found to predict worse glycemic control in COVID-19 patients, reflecting how inflammation interacts with metabolic processes." (PMID 39595206, 2024). "Indeed, multiple studies have reported increased levels of inflammatory or coagulation markers such as IL-6, CRP, C-reactive proteins, procalcitonin, ferritin and D-dimers in more severe forms of COVID-19 compared to less severe ones." (PMID 38814977, 2024). "The COVID-19 patients had lower levels of CRP and procalcitonin, and higher CE levels may, in part, reflect less inflammation in these patients." (PMID 39311203, 2024). "In a previous study regarding CK in COVID-19, high CK was associated with disease severity, even when adjusted for CRP values, without association with skeletal muscle symptoms." (PMID 38999510, 2024). "Elevated CRP levels are commonly observed in COVID-19 patients." (PMID 39866999, 2024). "However, a rapid and sustained decrease in CRP levels was reported in COVID-19 patients receiving tocilizumab, which is an IL-6 receptor monoclonal antibody." (PMID 38655258, 2024). "Interestingly, CRP, IL6 and IP10 had the most robust association with hospitalization and severe COVID-19, with CRP having the highest discriminatory capacity for hospitalization, and IL6 for severe COVID-19." (PMID 39664394, 2024). "Additionally, both observational study and meta-analysis supported CRP as a prognostic factor in assessing disease lethality for COVID-19 patients." (PMID 38698064, 2024). "This formulated panel is based on retrospective studies of several thousand patients with COVID-19, which have revealed the presence of elevated blood levels of C-reactive protein (CRP), calprotectin, soluble platelet selectin (sP-selectin), and D-dimer in these patients." (PMID 39661669, 2024). "However, this does not negate the importance of other haematological markers that have shown their value in predicting COVID-19-related mortality, such as C-reactive protein (CRP) and interleukin (IL)-6." (PMID 38674248, 2024). "Carriers of the minor allele of SNPs rs11203366, rs11203367, and rs874881 had CRP levels ≥9.9 mg/dL, an inflammation biomarker associated with poor clinical outcomes in patients with COVID-19." (PMID 38524554, 2024). "The biomarkers CRP, IL6, IP10, IL8, IL1RA, and suPAR showed also a good performance in identifying those participants at risk of developing severe COVID-19, defined as patients who required oxygen by non-invasive ventilation or high flow, intubation and mechanical ventilation, or who died." (PMID 39664394, 2024). "However, the authors note that COVID-19 patients with an increase in RHI had less severe systemic inflammation at baseline (reduced CRP and lower blood leukocytes and neutrophils)." (PMID 39598310, 2024). "There is also a recent guideline from the Royal College of Paediatrics and Child Health that recommended the use of CRP to decide whether to initiate immunomodulatory therapy in children with COVID-19." (PMID 38504318, 2024). "CRP is also used to monitor the response of COVID-19 treatment." (PMID 38450049, 2024). "Interestingly, the CRP has been identified as a relevant characteristic, significantly higher in severe COVID-19 patients, from data from the 4CE consortium." (PMID 38786571, 2024). "DPP-4i, being a gliptin drug representative, owing to its anti-inflammatory action, could be hypothesized to indirectly (through lowering the CRP concentration) affect the severity of COVID-19." (PMID 38540218, 2024). "However, our study found that markers like HOMA-IR and hs-CRP were more effective in predicting glycemic disturbances in COVID-19." (PMID 39595206, 2024). "Our analysis not only confirms previous findings indicating low adiponectin levels in severe COVID-19, but also suggests that a combination of low adiponectin and high CRP and procalcitonin levels may represent a novel biomarker signature for severe COVID-19." (PMID 38791005, 2024).